AATK (apoptosis associated tyrosine kinase)
Description:
May be involved in neuronal differentiation.
Synonyms: AATYK; p35BP; KIAA0641; LMR1; LMTK1; AATYK1; PPP1R77
Tractability: Small molecule: it belongs to a druggable protein family. Antibody: UniProt predicts a signal peptide or a membrane-spanning region.
Gene: Protein-coding gene on chromosome 17 (81,110,487 to 81,166,223, reverse strand). Ensembl gene ENSG00000181409.
Subcellular location: Membrane; Cytoplasm; Cytoplasm, perinuclear region
Subcellular location (Human Protein Atlas): Mitochondria
Gene Ontology:
Molecular function: protein binding; protein tyrosine kinase activity; ATP binding; protein kinase activity; protein serine kinase activity; protein serine/threonine kinase activity
Biological process: brain development; neuron apoptotic process
Cellular component: cytoplasm; endomembrane system; membrane; perinuclear region of cytoplasm
Genetic constraint (gnomAD): Loss-of-function variants: 91 observed, 68.81 expected, observed/expected ratio (o/e) 1.32, 90% interval 1.12 to 1.57. The synonymous counts are far from expectation, so gnomAD's model fits this gene poorly and the ratio says little. Missense variants: 2,169 observed, 1,555.3 expected, observed/expected ratio (o/e) 1.39, 90% interval 1.35 to 1.45. Synonymous variants: 1,068 observed, 742.39 expected, observed/expected ratio (o/e) 1.44, 90% interval 1.37 to 1.51.
Homologues: Orthologues: chimpanzee AATK (98% identical), macaque AATK (90% identical), pig AATK (76% identical), rat Aatk (73% identical), mouse Aatk (73% identical), dog AATK (70% identical), guinea pig AATK (70% identical), tropical clawed frog aatk (47% identical), zebrafish aatkb (45% identical), zebrafish aatka (37% identical). Paralogues in human: LMTK3 (31% identical).
Diseases named in the same sentence as AATK in open-access papers:
AATK is named in the same sentence as 59 diseases in open-access papers, as found by Europe PMC text mining. Sharing a sentence is not in itself a finding about the gene and the disease. The quoted sentences say what the papers report.
melanoma (7 papers, 2014 to 2024). A malignant, usually aggressive tumor composed of atypical, neoplastic melanocytes. "The overexpression of AATK in melanoma cells caused their growth arrest and induced apoptosis, whereas its epigenetic silencing was observed in human and murine cancer cell lines." (PMID 38978053, 2024). "Previous studies have shown that AATK overexpression causes apoptosis in melanoma cells." (PMID 32552862, 2020). "The knockdown of AATK expression caused a significant increase in CCND1 and WEE1 expression in the breast cancer cell line MCF-7, HEK293T and the melanoma cell line Sk-Mel13." (PMID 35902728, 2022). "Overexpression of AATK inhibits the growth of lung cancer and cervix cancer cells and is involved in apoptosis in melanoma." (PMID 32552862, 2020). "Tumor‐suppressive roles of the hosting AATK gene are well established in melanoma and lung cancer cells." (PMID 30913346, 2019). "Recent studies show AATK to promote apoptosis in melanoma cells and to be regulated by the Src kinase and in neurons to be important for recycling endosomes and synaptic vesicle transport." (PMID 25961023, 2015). "Recently, it has been reported that AATK inhibits cell proliferation, colony formation, migration, and also promotes apoptosis in melanoma cells." (PMID 25352953, 2014). "Since we observed hypermethylation of AATK in IGR1 melanoma cell lines, it will be interesting to analyze its methylation status in primary melanomas." (PMID 25352953, 2014). "AATK suppresses growth of melanoma cells, lung and cervix cancer cells." (PMID 35902728, 2022). "In melanoma cell lines, AATK suppresses growth and migration and promotes apoptosis." (PMID 32552862, 2020). "In melanoma cells AATK overexpression inhibits growth and migration, and promotes apoptosis." (PMID 25352953, 2014). "Downregulation of AATK expression was reported for adenocarcinoma of the colon and for melanomas." (PMID 25352953, 2014). "Thus, AATK hypermethylation may also be present in colon cancer and melanoma, as observed for the RASSF1A gene and other tumor suppressor genes." (PMID 25352953, 2014).
neuroblastoma (7 papers, 2009 to 2024). Neuroblastoma (NB) is the most common solid, extracranial childhood tumor. "A precise function for these receptors has yet to be defined, although LMR1 was identified as a potential marker of apoptosis, giving rise to the name AATYK (Apoptosis‐associated tyrosine kinase); while over‐expression induces differentiation in neuroblastoma cells." (PMID 29055036, 2017). "AATK was characterized as a novel kinase that induces and promotes neuronal differentiation in a human neuroblastoma cell line." (PMID 25352953, 2014). "Previous reports have demonstrated that retinoic acid-mediated neuronal differentiation of human neuroblastoma cells results in the synchronized induction of expression levels of miR-338-3p and its host gene AATK." (PMID 22363537, 2012). "It has been shown in a neuroblastoma cell-line that AATK gene produce neuronal differentiation." (PMID 29670510, 2018). "Here we propose a model, in which one of the two complementary versions of mature miR-338, namely miR-338-3p, generated through splicing and Dicer-mediated maturation, has the capacity to modulate the expression level of its host gene AATK in rat neuroblastoma cell lines." (PMID 22363537, 2012). "Despite the lack of a cis-acting binding site for miR-338-5p in rat AATK mRNA, our studies indicate that overexpression of this mature miRNA resulted in a modest reduction of host gene mRNA levels in rat neuroblastoma cell lines." (PMID 22363537, 2012). "Transfection of miR-338-3p mimics into rat B35 neuroblastoma cells resulted in a significant decrease of AATK mRNA levels, while the transfection of synthetic miR-338-5p mimics did not alter AATK levels." (PMID 22363537, 2012).
breast carcinoma (4 papers, 2014 to 2022). "PTGIR is associated with NSCLC and AATK is associated with other cancer types such as malignant glioma, lung and breast cancers." (PMID 26541675, 2015). "Initial evidence for potential epigenetic silencing of AATK has come from lung and breast cancer as well as pancreatic ductal adenocarcinoma." (PMID 35902728, 2022). "We validated their downregulation through overexpression of AATK in a kidney cell line and two glioblastoma cell lines and found their expression induced by RNAi of AATK in a breast cancer, a skin cancer and a kidney cell line." (PMID 35902728, 2022). "To date, epigenetic inactivation of AATK via promoter hypermethylation has been reported in pancreatic ductal adenocarcinoma, lung and breast cancer." (PMID 35902728, 2022). "Grippingly, downregulation of AATK expression can be found throughout tumor progression in breast cancer (BRCA), colon adenocarcinoma (COAD), HNSCC, lung cancer, and PAAD." (PMID 35902728, 2022). "Hypermethylation of AATK was also analyzed in 25 primary lung tumors, 30 breast cancers and 24 matching breast tissues." (PMID 25352953, 2014). "We observed that aberrant methylation of AATK is also frequently found in primary lung cancer (40%) and breast cancers (53%)." (PMID 25352953, 2014). "In our study we demonstrate that AATK is frequently hypermethylated in human cancer cell lines and in primary lung and breast cancer samples." (PMID 25352953, 2014). "Next we analyzed the aberrant methylation of AATK in 25 primary lung and 30 breast cancers by COBRA." (PMID 25352953, 2014). "This apparently contradictory result noted that AATK may have different role in breast cancer cell line MDA-MB-453." (PMID 25781993, 2015). "For breast cancer cell lines (MCF-7, ZR75-1), HeLa, LMS6/93, HEP2, Paca2, FTC133 and IGR1 partial methylation of AATK was also observed." (PMID 25352953, 2014).
lung carcinoma (4 papers, 2014 to 2022). "Further, loss of AATK expression has been linked to resistance to radiotherapy in the lung cancer cell line A549." (PMID 35902728, 2022). "Silencing of AATK leads to proliferation of pancreatic ductal cells and resistance to radiotherapy of lung cancer cells." (PMID 35902728, 2022). "In our study we report frequent epigenetic inactivation of AATK in different human cancer entities (e.g. breast and lung) and its growth suppressive function in lung cancer." (PMID 25352953, 2014). "To analyze the impact of epigenetic regulation of AATK in carcinogenesis we investigated its expression and methylation in normal tissues as well as in breast and lung cancer samples." (PMID 25352953, 2014). "The lung cancer cell line H322 has a methylated AATK promoter and shows very low endogenous AATK expression." (PMID 25352953, 2014). "Here we report that AATK hypermethylation is frequently found in other human epithelial cancers, including primary breast and lung cancers." (PMID 25352953, 2014). "Here we show that overexpression of CTCF induced the expression of AATK in HeLa and in the lung cancer cell lines A549 and H322." (PMID 25352953, 2014). "We have performed a genome wide methylation screen in the lung cancer cell line H322 and have revealed a promoter specific hypermethylation of the apoptosis associated tyrosine kinase (AATK) gene (data not shown)." (PMID 25352953, 2014). "Thus, aberrant methylation of AATK was observed in 10 out of 25 (40%) of lung cancer samples." (PMID 25352953, 2014). "Similarly, survival analyses for low WEE1 and high AATK expression indicate a higher survival probability in BRCA and lung cancer, HNSCC, and PDA." (PMID 35902728, 2022). "Furthermore, in BRCA and stage four HNSCC, in COAD, glioma (LGG), lung cancer, and PAAD, higher expression of AATK coincides with an increased overall survival probability." (PMID 35902728, 2022). "In addition, survival analyses indicate a higher survival probability for low CCND1 and high AATK expression in HNSCC, pancreatic ductal adenocarcinoma (PDA) and lung cancer (lung squamous cell carcinoma and adenocarcinoma)." (PMID 35902728, 2022). "All lung cancer cell lines (A549, A427, H322, H358 and HTB171) were partially methylated for AATK." (PMID 25352953, 2014).
pancreatic cancer (3 papers, 2014 to 2022). "The molecular mechanisms by which AATK affect the underlying subtype of transdifferentiation warrant further investigation, and further studies are needed to improve our understanding of the cell origin and clonal interactions of pancreatic cancer subtypes." (PMID 32552862, 2020). "Inhibition of DNA methyltransferases (DNMTs) reactivated AATK in glioblastoma and pancreatic cancer." (PMID 35902728, 2022). "Overall, the growth curves for cells with AATK overexpression compared to control in four pancreatic cancer cell lines showed the suppressed static growth rate in four cell lines examined." (PMID 32552862, 2020). "Apoptosis analysis of four pancreatic cancer cell lines with AATK overexpression compared to the empty vector and untransfected control cells showed increased apoptotic cells." (PMID 32552862, 2020). "The apoptosis-associated tyrosine kinase (AATK) gene is located at 17q25.3, a frequent LOH region in the chromosome 17q arm of pancreatic cancer samples characterized by array CGH and sequencing." (PMID 32552862, 2020). "siRNA knockdown of AATK expression in pancreatic cancer cell lines led to an upregulation of EMT genes." (PMID 32552862, 2020). "Hypermethylation of AATK was found in several epithelial cancer entities including lung, breast, skin, cervix, larynx and pancreatic cancer." (PMID 25352953, 2014). "In addition, we determined that the CGI of AATK was methylated in 100% of seven pancreatic cancer cell lines (Hup-T3, Capan-1, PATU-S, Capan-2, PATU-T, PaCa2, PATU-02) and pharmacologically inhibiting DNMTs with 5-Aza-2′-deoxycytidine led to demethylation and re-expression of AATK." (PMID 35902728, 2022).
gastric cancer (2 papers, 2021 to 2023). A primary or metastatic malignant neoplasm involving the stomach. "Previous researches have elucidated the function of circRNA from the view of ceRNA, such as circPTK2-repressed gastric cancer cell growth and invasion via targeting miR-196a-3p and downregulating AATK protein expression." (PMID 37588107, 2023). "Regarding prognosis, Kaplan–Meier curves showed that low AATK expression correlated with poor survival rate of patients of gastric cancer." (PMID 34604044, 2021). "Collectively, AATK is a direct target gene of miR-196a-3p and is downregulated in gastric cancer tissues." (PMID 34604044, 2021). "Collectively, circPTK2 could induce the apoptosis of gastric cancer cells by regulating the miR-196a-3p/AATK/STK39/p39 pathways." (PMID 34604044, 2021). "In agreement with a previous study, we found that AATK was downregulated in gastric cancer cells." (PMID 34604044, 2021). "Mechanistically, circPTK2 could suppress the proliferation, migration, and invasion of gastric cancer cells through directly binding to miR-196a-3p and subsequently decrease the inhibiting ability of miR-196a-3p on AATK." (PMID 34604044, 2021). "Collectively, circPTK2 functions as a tumor suppressor to suppress gastric cancer cell proliferation, migration, and invasion through regulating the miR-196a-3p/AATK axis, suggesting that circPTK2 may serve as a novel therapeutic target for gastric cancer." (PMID 34604044, 2021). "Furthermore, the expression of AATK was notably downregulated in gastric cancer tissues." (PMID 34604044, 2021). "The results showed that AATK could bind with STK39 in gastric cancer cell contexts." (PMID 34604044, 2021). "In addition, circPTK2 could inhibit the proliferation, migration, and invasion of gastric cancer cells through functioning as a miRNA sponge to upregulate the expression of the tumor-suppressor gene AATK." (PMID 34604044, 2021). "In addition, overexpression of circPTK2 markedly upregulated the expression of AATK in gastric cancer cells, suggesting that circPTK2 could interact with miR-196a-3p and function as a miRNA sponge to regulate AATK expression." (PMID 34604044, 2021). "In addition, upregulation of circPTK2 could inhibit gastric cancer cell proliferation, migration, and invasion by targeting the miR-196a-3p/AATK axis." (PMID 34604044, 2021). "Importantly, the association of AATK with the development of gastric cancer has not been described." (PMID 34604044, 2021). "Our data indicated that overexpression of AATK notably downregulated the expressions of p-STK39 and p-p38 in gastric cancer cells, suggesting that AATK might inhibit gastric cancer progression via inactivating the STK39/p38 signaling pathway." (PMID 34604044, 2021).
acute pancreatitis (1 paper, 2022). An acute inflammatory process that leads to necrosis of the pancreatic parenchyma. "Further, via pyrosequencing, we found that the mean methylation of the promoter CGI of AATK was significantly higher in pancreatic adenocarcinoma (PAAD > 22%) and acute pancreatitis (>20%) compared to normal tissues (10%)." (PMID 35902728, 2022).
astrocytoma (1 paper, 2022). "In respect to the observed results, we analyzed the methylation of the CGI of AATK in eight glioblastoma cell lines (LN229, U343, U118, U87MG, T98G, A172, U251, LNZ308), one glioma (A764) and one astrocytoma (SNB19) cell line." (PMID 35902728, 2022).
B-cell lymphoma (1 paper, 2021). "In primary lymphoma samples, AATK/miR-1250 was frequently methylated in B-cell lymphoma (n = 41, 44.09%) and T-cell lymphoma (n = 9, 33.33%) with a comparable frequency (P = 0.318)." (PMID 34044822, 2021). "AATK/miR-1250 methylation was detected in 41 (44.09%) B-cell NHL and 9 (33.33%) T-cell NHL cases, hence AATK/miR-1250 were frequently hypermethylated in both B-cell and T-cell NHL with a comparable frequency (P = 0.318)." (PMID 34044822, 2021). "As AATK/miR-1250 was frequently methylated in NHL primary samples, the tumor suppressor function of miR-1250-5p was studied by overexpression of miR-1250-5p in completely methylated NHL cells, including B-cell lymphoma SU-DHL-6 cells and T-cell lymphoma SU-DHL-1 cells." (PMID 34044822, 2021).
glioblastoma (1 paper, 2022). The most malignant astrocytic tumor (WHO grade IV). "The expression of CCND1 is decreased in HEK293T and the glioblastoma cell line U343 after overexpression of EYFP-tagged AATK wt in comparison to EYFP-tagged AATK KD or EYFP empty." (PMID 35902728, 2022). "78% of the glioblastoma cell lines were methylated and reduced expression of AATK was observed in 7 out of 8 cell lines." (PMID 35902728, 2022). "Upon pharmacological inhibition of DNMTs with 5-Aza-2′-deoxycytidine in the glioblastoma cell line U87MG, a slight decrease in methylation of AATK as well as re-expression of AATK were observed." (PMID 35902728, 2022).
glioma (1 paper, 2022). A benign or malignant brain and spinal cord tumor that arises from glial cells (astrocytes, oligodendrocytes, ependymal cells). "In our study, we specifically investigated the epigenetic inactivation of AATK in pancreatic adenocarcinoma, lower grade glioma, lung, breast, head, and neck cancer." (PMID 35902728, 2022). "Via Geo2R, we analyzed the promoter CGI (cg15665342, cg26717786) and eight CpG sites in the shore regions of AATK in normal brain (Corpus callosum) and glioma (GII) samples." (PMID 35902728, 2022). "The glioma cell line was also strongly methylated and AATK expression was as entirely undetectable." (PMID 35902728, 2022).
head and neck squamous cell carcinoma (1 paper, 2022). A squamous cell carcinoma that arises from any of the following anatomic sites: lip and oral cavity, nasal cavity, paranasal sinuses, pharynx, larynx, and salivary glands. "In head and neck squamous cell carcinoma (HNSCC), we analyzed the AATK methylation in matching normal and tumor samples, finding 36% of the tumor samples significantly higher methylated than the matching normal sample." (PMID 35902728, 2022).
lung adenocarcinoma (1 paper, 2014). A carcinoma that arises from the lung and is characterized by the presence of malignant glandular epithelial cells. "Four out of five lung adenocarcinomas (e.g. TA59) exhibited a partial methylation of AATK." (PMID 25352953, 2014).
lymphoma (1 paper, 2021). A malignant (clonal) proliferation of B- lymphocytes or T- lymphocytes which involves the lymph nodes, bone marrow and/or extranodal sites. "AATK/miR-1250 methylation was studied in healthy controls, including ten normal peripheral blood buffy coats and eleven normal tonsils, ten lymphoma cell lines, and 120 primary lymphoma samples by methylation-specific PCR (MSP)." (PMID 34044822, 2021).
non-Hodgkin lymphoma (1 paper, 2021). Distinct from Hodgkin lymphoma both morphologically and biologically, non-Hodgkin lymphoma (NHL) is characterized by the absence of Reed-Sternberg cells, can occur at any age, and usually presents as a localized or generalized lymphadenopathy associated with fever and weight loss. "As a CpG island is present at the putative promoter region of its host gene, AATK, we postulated that the intronic miR-1250-5p is a tumor suppressor miRNA co-regulated with its host gene, AATK, by promoter DNA methylation in non-Hodgkin’s lymphoma (NHL)." (PMID 34044822, 2021).
oral cancers (1 paper, 2014). "It is interesting to note that deletion of the chromosomal region which harbors the AATK gene is observed in different tumor entities including breast, cervix and oral cancers." (PMID 25352953, 2014).
pancreatic adenocarcinoma (1 paper, 2022). "In this study, we characterize the loss of AATK expression due to promoter hypermethylation and the coinciding poorer overall survival probability in breast, colon, head and neck, lung, and pancreatic adenocarcinoma." (PMID 35902728, 2022).